YTHDF2 (YTH N6-methyladenosine RNA binding protein F2)
Diseases named in the same sentence as YTHDF2 in open-access papers (continued):
Sharing a sentence is not in itself a finding about the gene and the disease.
breast carcinoma (continued). "Apoptosis was shown to be triggered by the inhibition of YTHDF2-dependent mRNA degradation in TNBC through MAPK pathway-dependent induction of the EMT, and increased the global translation of mRNA synthesis in MYC-driven breast cancers." (PMID 35721510, 2022). "The study also indicated that YTHDF2 was crucial to the survival of TNBC cells, while it is dispensable for cells that were less dependent on high expression levels of MYC, suggesting the elusive role of YTHDF2 in breast cancer." (PMID 35382893, 2022). "Either overexpression or knockdown of YTHDF2 did not alter the expression level of tumor suppressor genes in breast cancer." (PMID 35382893, 2022). "The combination of YTHDF2 and YAP mRNA reduces the stability of mRNA, while YTHDF2 recruits AGO2 (argonaute RISC catalytic component 2) to promote the degradation of YAP mRNA, affecting the production of related tumor factors and inhibiting the occurrence of tumors in breast cancer." (PMID 41597255, 2026). "Based on the results, it was hypothesized that YTHDF2 may promote LUSC cell proliferation by activating the AKT/mTOR signaling pathway which is known to play a pivotal role in multiple types of cancer, such as breast cancer and ovarian carcinoma." (PMID 34996459, 2022). "However, expression of YTHDF2 was recently reported to be elevated in MYC-driven TNBC compared with hormone receptor-positive and human epidermal growth factor receptor 2 positive breast cancers." (PMID 35382893, 2022). "In other words, elevated YTHDF2 expression in FTO silencing breast cancer cells could not inverse the increasing of BNIP3 mRNA expression, indicating the presence of alternative mechanism to stabilize m6A-modified BNIP3 mRNA." (PMID 30922314, 2019).
gastric cancer (37 papers, 2019 to 2025). A primary or metastatic malignant neoplasm involving the stomach. "A Kaplan-Meier survival analysis was conducted to investigate the association between elevated YTHDF2 expression and poor prognosis in patients with gastric cancer." (PMID 41323282, 2025). "The expression level of YTHDF2 was inversely associated with gastric cancer patients’ tumor size, AJCC classification and prognosis." (PMID 36870954, 2023). "Targeting the YTHDF2/PPP2CA axis may be a potential therapeutic strategy against gastric cancer and YTHDF2 might become a hopeful diagnostic biomarker for this disease in the future." (PMID 36870954, 2023). "Using gain-of-function or loss-of-function assays, we identified that YTHDF2 suppressed gastric cancer cell proliferation and migration in vitro and in vivo, supporting a cancer-suppressing function of YTHDF2 in gastric cancer, consistent with previous related studies." (PMID 36870954, 2023). "Growing evidence implicates that YTHDF2 takes an indispensable part in the regulation of tumorigenesis and metastasis in different cancers, but its biological functions and underlying mechanisms remain elusive in gastric cancer (GC)." (PMID 36870954, 2023). "We conducted a tissue microarray analysis on paired samples from 149 patients with gastric cancer to validate the differential expression of YTHDF2 between tumor and normal tissues." (PMID 41323282, 2025). "The impact of niclosamide and YTHDF2, an m6A methylation regulator, on gastric cancer cell proliferation was investigated both in vitro and in vivo." (PMID 41323282, 2025). "In order to identify efficacious pharmacological agents capable of modulating YTHDF2 and ameliorating gastric cancer progression, we employed network pharmacology analysis." (PMID 41323282, 2025). "The findings suggest that YTHDF2 potentially affects gastric cancer metabolic pathways through gene modulation." (PMID 41323282, 2025). "Flow cytometry analysis further substantiated these observations, showing an increase in cell apoptosis in response to escalating niclosamide concentrations and YTHDF2 knockdown, thereby impeding the progression of gastric cancer." (PMID 41323282, 2025). "Our research highlights the essential function of YTHDF2 in the metabolism and clinical features of gastric cancer." (PMID 41323282, 2025). "YTHDF2 significantly influences gastric cancer metabolism, metastasis, and prognosis, indicating its potential as a target for therapy." (PMID 41323282, 2025). "This indicates a significant link between high levels of YTHDF2 expression and unfavorable outcomes in patients with gastric cancer." (PMID 41323282, 2025). "We also assessed YTHDF2 expression across different stages of gastric cancer (T1-T4) and its relationship with the proliferation marker KI67." (PMID 41323282, 2025). "The m6A modification of its downstream gene ULK1 can be removed by FTO, thus protecting it from targeted degradation by YTHDF2 and playing a role in cisplatin resistance in gastric cancer (GC)." (PMID 39468015, 2024). "Subsequently, gain-of-function assays were implemented to investigate the effects of YTHDF2 overexpression in gastric cancer cell lines, such as HGC27 and MGC803." (PMID 36870954, 2023). "These collective findings highlighted the potential functions of YTHDF2 in gastric cancer development." (PMID 36870954, 2023). "Functionally, YTHDF2 reduction facilitated gastric cancer cell growth and migration in vitro and in vivo, whereas YTHDF2 overexpression exhibited opposite phenotypes." (PMID 36870954, 2023). "The nude mouse xenograft models were established through subcutaneous injection of gastric cancer cells in which YTHDF2 was stably overexpressed or knocked down, respectively." (PMID 36870954, 2023). "Compared with matched normal stomach tissues, YTHDF2 expression was markedly decreased in gastric cancer tissues." (PMID 36870954, 2023).
gastric cancer (continued). "Compared with normal tissues, YTHDF2 was significantly upregulated in gastric cancer, Silencing of YTHDF2 suppressed gastric cancer cell multiplication, arresting the cell cycle in the G1/S phase and boosting cell apoptosis." (PMID 36017491, 2022). "In vitro studies have shown that the knockdown of YTHDF2 can inhibit the proliferation of gastric cancer cells and promote their apoptosis." (PMID 33692959, 2021). "In vitro assay revealed that YTHDF2 slience inhibited gastric cancer cell proliferation, arrested cell in G1 phase, and accelerated cell apoptosis." (PMID 33593354, 2021). "YTHDF2 was found to be significantly up-regulated in gastric cancer tissues compared with that in normal tissues." (PMID 33593354, 2021). "A recent study suggests that phosphatase and tensin homolog (PTEN) mRNA degradation depends on the m6A reader protein YTHDF2 in gastric cancer cells." (PMID 33363140, 2020). "As previously reported, YTHDF2 decreased PTEN expression by recognizing the PTEN m6A modification pathway in gastric cancer cells." (PMID 33363140, 2020). "The YTHDF2-dependent decay of m6A-modified AC026691.1 transcripts may drive proliferative capacity in gastric cancer." (PMID 40986143, 2025). "We also checked into the link between increased YTHDF2 expression and gastric cancer metastasis." (PMID 41323282, 2025). "Furthermore, YTHDF2 exhibits elevated expression in gastric cancer cells, while AC026691.1 shows downregulated expression." (PMID 40986143, 2025). "Importantly, YTHDF2-mediated m6A modification of one cut homeobox 2 (ONECUT2) can promote stemness in gastric cancer." (PMID 40986143, 2025). "Scatterplot analysis revealed a strong positive relationship between YTHDF2 expression levels and lymph node metastasis count (r = 0.24), indicating that elevated YTHDF2 expression may facilitate lymphatic metastasis in gastric cancer." (PMID 41323282, 2025). "YTHDF2 exhibits divergent expression patterns and functional roles in gastric cancer (GC)." (PMID 39342406, 2024). "Nevertheless, the study on YTHDF2 in gastric cancer is limited." (PMID 36870954, 2023). "More importantly, we suggested that YTHDF2 could suppress the progression of gastric cancer via regulating PPP2CA and exert a tumor suppressor effect in an m6A-independent manner for the first time." (PMID 36870954, 2023). "In our study, we disclosed that compared with paired normal adjacent stomach tissues, the expression level of YTHDF2 was frequently down-regulated in gastric cancer tissues, whereas down-regulated YTHDF2 expression was relevant to larger tumor sizes, higher TNM stages and poorer survival status." (PMID 36870954, 2023). "YTHDF2 reduced cell growth by targeting FOXC2 pathway in gastric cancer." (PMID 36003776, 2022). "In recent years, studies focus on the biological role of YTHDF2 in gastric cancer." (PMID 33593354, 2021). "YTHDF2 can be used as a new target to study the mechanism of gastric cancer." (PMID 33692959, 2021). "For example, YTHDF1, YTHDF2, and especially METTL3 are associated with gastric cancer." (PMID 34277622, 2021). "Overexpression of YTHDF2 significantly inhibited the proliferation, invasion and migration of gastric cancer cells by negatively regulating forkhead box C2 (FOXC2), which acts as an oncogene in various cancers such as nasopharyngeal cancer, colorectal cancer and triple negative breast cancer." (PMID 33928028, 2021). "It was elaborated that YTHDF2 recognized the PTEN m6A modification pathway in gastric cancer cells." (PMID 33363140, 2020). "In addition, we also tested the effect of YTHDF2 on the migration and invasion of gastric cancer cells." (PMID 33505426, 2020). "Furthermore, Transwell assays revealed that both niclosamide treatment and YTHDF2 knockdown (YTHDF2-KD) diminished cell migration and invasion capabilities, suggesting that niclosamide may impede gastric cancer metastasis." (PMID 41323282, 2025).
gastric cancer (continued). "Knockdown of PPP2CA mitigated GC cells’ cisplatin sensitivity originally caused by YTHDF2 up-regulation as presented by CCK8 analysis, prompting that YTHDF2/PPP2CA regulatory axis may play a partial role in the drug sensitivity of gastric cancer cells." (PMID 36870954, 2023). "In addition, YTHDF2 is down-regulated in gastric cancer tissues and cells." (PMID 33928028, 2021). "However, it is unclear whether YTHDF2 also regulates the mRNA stability of oncogenes in gastric cancer." (PMID 33505426, 2020). "STUB1 is recognized as a tumor suppressor in liver, prostate, lung, and gastric cancers through the degradation of key oncogenic proteins, such as JMJD1A, YAP1, AR1, and YTHDF2." (PMID 40859326, 2025). "YTHDF2 is downregulated, and its overexpression facilitates ONECUT2 mRNA degradation through m6A modification in gastric cancer." (PMID 40986143, 2025). "Taken together, these data demonstrated that YTHDF2 is down-regulated in gastric cancer, and its expression is negatively correlated with the prognosis and progression of GC patients, implicating that YTHDF2 might act as a prospective biomarker in GC." (PMID 36870954, 2023). "LncRNA CBSLR affects the m6A modification of CBS by acting on YTHDF2, and high expression of CBSLR leads to poor prognosis of gastric cancer patients." (PMID 37781080, 2023). "In gastric cancer, m6A modifications are mediated by the CNV deletions of ELAVL1, YTHDF2 and FMR1, which then affects tumor formation." (PMID 33926554, 2021). "In gastric cancer, studies have shown that the degradation of PTEN mRNA mediated by LINC00470-METTL3 depends on the m6A read protein YTHDF2-dependent pathway to promote the malignant behavior of gastric cancer cells." (PMID 33505426, 2020). "The m6A reader protein YTHDF2 mediates the m6A modification of ONECUT2 mRNA, thereby activating TFPI transcription, leading to stemness in gastric cancer and resistance to oxaliplatin, providing a new treatment target to tackle gastric cancer that is resistant to oxaliplatin." (PMID 41584846, 2025). "Besides, Shen found that YTHDF2 recognized and mediated the m6A modification of FOXC2 and restrained gastric cancer cell growth via degrading FOXC2, but which “writer” added the m6A modification of FOXC2 mRNA in this study was still unclear." (PMID 36870954, 2023). "To investigate whether YTHDF2 has a unified function in EBV reactivation regardless of cell type and lytic induction methods, we knocked out YTHDF2 in another Burkitt lymphoma cell line, P3HR-1, and a gastric cancer cell line, SNU-719." (PMID 34425696, 2021). "However, the effect of YTHDF2 on gastric cancer and the molecular mechanism of this effect have not been documented." (PMID 33505426, 2020).
colorectal cancer (35 papers, 2020 to 2026). A primary or metastatic malignant neoplasm that affects the colon or rectum. "KRT17 is upregulated in mismatch repair-deficient colorectal cancer, where it enhances T cell infiltration via the YTHDF2/CXCL10 signaling axis, thereby reversing immune evasion." (PMID 40986143, 2025). "For instance, METTL14, which is underexpressed in colorectal cancer (CRC) and linked to a poor prognosis, reduces m6A levels on XIST and enhances YTHDF2-mediated XIST expression, thereby inhibiting tumor cell growth." (PMID 40271153, 2025). "Prior studies have shown that in colorectal cancer and esophageal squamous cell carcinoma, YTHDF2 activates this pathway by targeting m6A-modified GSK3β and APC mRNAs for degradation." (PMID 38637831, 2024). "In vitro and in vivo experiments testified that upregulation of miR-6125 prevents the proliferation phenomenon of colorectal cancer through the direct mediation of YTHDF2." (PMID 36875073, 2023). "MiR-6125 reduces the expression of cyclin D1 to generate the result of arrest at the G0/G1 phase of colorectal cancer cells, which depends on YTHDF2 mediating to take part in Wnt/β-catenin cascades." (PMID 36875073, 2023). "YPEL5 was found to be inhibited by METTL3-m6A (N6-methyladenosine)-YTHDF2 axis in colorectal cancer, promoting the growth and metastasis of tumor." (PMID 35265613, 2022). "YTHDF2 mediates the attenuation of oncogenic mRNAs and participates in the inhibition of colorectal cancer or enhances the anti-tumor effect of natural killer cells." (PMID 34544449, 2021). "For instance, METTL3 facilitated the tumorigenesis and metastasis of colorectal cancer by inhibiting YPEL5 expression in a YTHDF2 (an m6A reader)-dependent manner." (PMID 34950654, 2021). "Furthermore, SMAD4 overexpression enhances NKG2D activation via YTHDF2 upregulation, thereby potentiating NK cell cytotoxicity against colorectal cancer cells through the SMAD4/YTHDF2 regulatory axis." (PMID 40986143, 2025). "Similarly, miR‐6125 has been shown to downregulate YTHDF2 and inhibit the growth of colorectal cancer cells by downregulating cyclin D1." (PMID 40231553, 2025). "Therefore, we silenced YTHDF2 in colorectal cancer cell lines and observed an increase in the stability of SNAIL mRNA." (PMID 38605400, 2024). "Interestingly, the YTHDF2-dependent pathway relied on by METTL14-related regulation has been discovered previously in colorectal cancer." (PMID 36288387, 2022). "For example, the expression of M6A “writer” protein methyltransferase-like 14 (METTL14) is downregulated in colorectal cancer, and it has been found that XIST is downregulated by METTL14 in a YTHDF2-dependent way, which is responsible for inhibiting the growth of colorectal cancer." (PMID 36035993, 2022). "However, whether the up-regulation of YTHDF1 and YTHDF2 is effective for patients with colorectal cancer needs further research." (PMID 35069586, 2021). "METTL14 reportedly curbs the metastasis of colorectal cancer cells by inhibiting the m6A modification of SRY-box transcription factor 4 (SOX4) mRNA, a mechanism reliant on the YTHDF2-mediated mRNA degradation pathway." (PMID 40746896, 2025). "Similar to other tumors, the regulation of m6A modifications in colorectal cancer is equally diverse and complex, and almost all m6A modifiers except METTL14, ZC3H13, METTL3, FTO, ALKBH5, and YTHDF2 promote colorectal carcinogenesis." (PMID 39967906, 2025). "In a word, inhibiting AKT activated ferroptosis through FTO/YTHDF2/GPX4 axis to suppress colon cancer progression, which raised FTO/GPX4 as potential biomarkers and targets in colorectal cancer therapy." (PMID 38102129, 2023). "METTL14 knockout reduces the m6A level of downstream XIST, which can’t be recognized by YTHDF2 and inhibits its degradation, promotes the expression of XIST, and promotes the progress of colorectal cancer." (PMID 35022030, 2022).
colorectal cancer (continued). "For example, METTL3 promotes colorectal cancer by activating the m6A-GLUT1-mTORC1 axis; YTHDF2 mediates lipopolysaccharide-induced osteoclastogenesis and inflammatory response via the NF-κB and MAPK signaling pathways." (PMID 35794625, 2022). "However, all the SNPs including YTHDF2 rs4654320 could not predispose to colorectal cancer, except for one SNP rs118049207 in the SND1 gene." (PMID 34539889, 2021). "Additionally, co-inhibition of YTHDF2, ATF4-induced autophagy, and glutamine provides a novel strategy for targeted therapy in colorectal cancer." (PMID 35794625, 2022).